TRIM9 (tripartite motif containing 9)
Description:
E3 ubiquitin-protein ligase which ubiquitinates itself in cooperation with an E2 enzyme UBE2D2/UBC4 and serves as a targeting signal for proteasomal degradation. May play a role in regulation of neuronal functions and may also participate in the formation or breakdown of abnormal inclusions in neurodegenerative disorders. May act as a regulator of synaptic vesicle exocytosis by controlling the availability of SNAP25 for the SNARE complex formation.
Synonyms: RNF91; SPRING
Tractability: PROTAC: UniProt records ubiquitination sites on it; its protein half-life has been measured.
Gene: Protein-coding gene on chromosome 14 (50,975,261 to 51,096,078, reverse strand). Ensembl gene ENSG00000100505.
Subcellular location: Cytoplasm; Cell projection, dendrite; Cytoplasmic vesicle, secretory vesicle, synaptic vesicle; Synapse; Cytoplasm, cytoskeleton
Pathways (Reactome):
Immune System: Antigen processing: Ubiquitination & Proteasome degradation
Gene Ontology:
Molecular function: protein binding; protein domain specific binding; protein homodimerization activity; ubiquitin protein ligase activity; metal ion binding; zinc ion binding
Biological process: proteasome-mediated ubiquitin-dependent protein catabolic process; protein ubiquitination
Cellular component: cytoplasm; dendrite; cytoskeleton; synapse; synaptic vesicle
Genetic constraint (gnomAD): Loss-of-function variants: 20 observed, 71.43 expected, observed/expected ratio (o/e) 0.28, 90% interval 0.2 to 0.41. The upper end of that interval is the gene's LOEUF score, 0.41, which puts it in group 1 of 6, group 1 being the genes least tolerant of losing a copy. Missense variants: 771 observed, 1,039.6 expected, observed/expected ratio (o/e) 0.74, 90% interval 0.7 to 0.79. Synonymous variants: 395 observed, 416.44 expected, observed/expected ratio (o/e) 0.95, 90% interval 0.87 to 1.03.
Homologues: Orthologues: pig TRIM9 (98% identical), rat Trim9 (98% identical), macaque TRIM9 (97% identical), chimpanzee TRIM9 (97% identical), rabbit TRIM9 (96% identical), dog TRIM9 (96% identical), guinea pig TRIM9 (95% identical), mouse Trim9 (87% identical), tropical clawed frog trim9 (83% identical), zebrafish trim9 (73% identical). Paralogues in human: TRIM67 (61% identical), TRIM46 (24% identical), TRIM36 (22% identical), TRIM24 (16% identical), TRIM33 (16% identical), TRIM37 (15% identical), TRIM3 (14% identical), MID2 (14% identical), TRIM2 (14% identical), MID1 (14% identical), TRIM66 (13% identical), TRIM71 (13% identical), and 68 more.
Diseases named in the same sentence as TRIM9 in open-access papers:
TRIM9 is named in the same sentence as 38 diseases in open-access papers, as found by Europe PMC text mining. Sharing a sentence is not in itself a finding about the gene and the disease. The quoted sentences say what the papers report.
breast carcinoma (5 papers, 2015 to 2024). "The aim of the present study was therefore first to investigate whether methylation of TRIM9 promoter is associated with its gene expression in breast cancer cells, and second to clarify the clinicopathological characteristics of TRIM9 methylated breast tumors." (PMID 26543769, 2015). "Research shows that TRIM9 is low expressed in breast cancer, significantly inhibits the ubiquitination level of oncogene and promotes its protein expression and function." (PMID 38263865, 2024). "Methylated TRIM9, which suppressed the TRIM9 mRNA expression, was reported to serve as a blood biomarker in breast cancer patients." (PMID 37249822, 2023). "Previous studies indicated that TRIM9 (Tripartite Motif Containing 9) is a potential marker in breast cancer patients." (PMID 37124931, 2023). "To study the methylation status of TRIM9 in human breast cancer and normal breast tissues, we performed an NGS methylation assay using the 19 paired tumor and normal tissues (study I)." (PMID 26543769, 2015). "Bisulfite sequencing with a next generation sequencer showed TRIM9 promoter methylation in 92 % (11/12) of breast cancer cell lines (BCCs) and 68 % (13/19) of breast tumor tissues but not in any normal breast tissues (0/19)." (PMID 26543769, 2015). "Using the Illumina Human Methylation 450 database, we found TRIM9 is specifically methylated in breast cancer tissues." (PMID 26543769, 2015). "The aim of the present study wasto investigate the promoter methylation status of TRIM9 in breast cancer and to determine the presence of TRIM9-methylated circulating tumor DNA (ctDNA) in plasma." (PMID 26543769, 2015). "And high TRIM9 promoter methylation status was correlated with significantly suppressed TRIM9 mRNA levels, which could be a potential biomarker for breast cancer." (PMID 37124931, 2023). "While in breast cancer, the expression of TRIM9 was inhibited due to the methylation of TRIM9 promoter and TRIM9 methylation of DNA could be used as a tumor marker of breast cancer." (PMID 31028132, 2019). "TRIM9-methylated ctDNA may thus be a potential tumor marker and might work better in combination with other blood biomarkers for breast cancers to compensate for its lower sensitivity." (PMID 26543769, 2015). "Although the regulatory mechanism of TRIM9 gene expression and its biological functions remain unclear, our preliminary results suggest that methylated TRIM9 may serve as a novel blood biomarker specific to breast cancer patients." (PMID 26543769, 2015). "Lastly, we examined whether TRIM9 methylated ctDNA can be detected in plasma of breast cancer patients and explored its utility as a novel blood biomarker for breast cancer diagnosis." (PMID 26543769, 2015). "Moreover, methylated TRIM9 was reported to be abnormally expressed in breast tumor tissues and plasma in metastatic breast cancer patients, and can serve as a novel blood biomarker in breast cancer." (PMID 37249822, 2023). "TRIM9, as a component of the TRIM family, has been demonstrated as a potential biomarker for breast cancer detection." (PMID 37124931, 2023). "TRIM9 methylated ctDNA in plasma was detected in 18 % (10/56) of metastatic breast cancer patients but not in any of 60 healthy controls." (PMID 26543769, 2015).
uterine fibroids (4 papers, 2023 to 2024). "In uterine fibroids, TRIM9 is overexpressed and regulates cyclin D1, survivin, lysed caspase 3 and nuclear NF‐κB to enhance cell proliferation, reduces apoptosis and significantly promotes the growth of uterine fibroids." (PMID 38263865, 2024). "TRIM9 encodes an E3 ubiquitin-protein ligase; studies have shown that TRIM9 can promote the occurrence and development of uterine fibroids through the NF-κB signaling pathway." (PMID 36611207, 2023). "Meanwhile, TRIM9 overexpression was reported to promotes uterine leiomyoma progression via enhancement of cell proliferation, reduction of cell apoptosis and regulation of cell cycle and nuclear NF-κB expression." (PMID 37249822, 2023). "Meanwhile, an interesting observation was also reported in uterine leiomyoma, suggesting that TRIM9 overexpression enhanced cell proliferation and antiapoptosis by boosting the activities of subsequent prosurvival signal pathways including survivin and NF-κB." (PMID 37124931, 2023). "More recently, TRIM9 overexpression was shown to promote uterine leiomyoma development through NF-κB signaling pathway." (PMID 37249822, 2023).
dementia (3 papers, 2014 to 2024). Loss of intellectual abilities interfering with an individual's social and occupational functions. "TRIM9 immunoreactivity was shown to be diminished in affected brain areas in Parkinson’s disease and dementia with Lewy bodies, indicating a possible role for TRIM9 in neurodegenerative diseases." (PMID 30208054, 2018). "Finally, TRIM9/SPRING has been described as repressed in the brains of individuals suffering from Parkinson’s disease and dementia with Lewy bodies." (PMID 39205302, 2024).
ischemic stroke (3 papers, 2019 to 2024). A stroke disorder caused by obstruction of blood flow to the brain, due to thrombotic (local blood clot formation) or embolic (due to a blood clot or other material traveling from another site) event. "Upon ischemic stroke, TRIM9 inhibits NF‐κB‐mediated neuroinflammation by stabilizing IκBα, resulting in alleviated cerebral damage." (PMID 38778460, 2024). "NF-κB suppression by TRIM9 is also important during ischemic stroke, where TRIM9 upregulation in the peri-infarct area is anti-inflammatory and neuroprotective." (PMID 38115822, 2023).
bladder cancer (2 papers, 2023 to 2025). "Fourteen TRIM family proteins were associated with bladder cancer (tumor-promoting: TRIM9, TRIM25, TRIM26, TRIM28, TRIM29, TRIM59, TRIM65, and TRIM66; tumor-suppressive: TRIM19 and TRIM38)." (PMID 40723250, 2025). "Our study found a significantly elevated CEACAM6 expression in TRIM9 high expressed bladder cancer and it was associated with poor survival of patients." (PMID 37249822, 2023). "In the present study, we investigated the underlying association between TRIM9 expression and the development of bladder cancer in vitro and in vivo." (PMID 37249822, 2023). "First, the transcriptional analysis of the TCGA database indicated that TRIM9 was associated with high clinicopathological stage and poor survival in bladder cancer patients." (PMID 37249822, 2023). "TRIM9 and its associated molecules could be a potential diagnostic indicator and therapeutic target in bladder cancer." (PMID 37249822, 2023). "To identify the role of TRIM9 during bladder cancer progression, we first analyzed its transcriptome expression in 296 bladder tumor tissues by utilizing TCGA database." (PMID 37249822, 2023). "The findings suggested that TRIM9 was upregulated in bladder cancer patients with high clinical stages (stage III ~ IV), when compared to those from low clinical stages (stage I ~ II)." (PMID 37249822, 2023). "Aberrant high expression of TRIM9 in bladder cancer correlates to poor survival and is an independent prognostic factor associated with a higher risk of relapse in bladder patients." (PMID 37249822, 2023). "Our results revealed the molecular mechanisms by which TRIM9 facilitates tumor growth, metastasis and chemoresistance in bladder cancer, and provided a promising combined therapy strategy to improve the outcome of chemotherapy." (PMID 37249822, 2023). "This study was the first, to our best knowledge, to explore the important role of TRIM9 in bladder cancer and provide a novel prognostic biomarker for clinical early diagnosis." (PMID 37249822, 2023). "We initially determined that the upregulated TRIM9 was closely correlated to the clinical stages, tumor recurrence and poor survival in bladder cancer patients." (PMID 37249822, 2023). "Remarkably, this study, for the first time, indicated that CEACAM6 played an important role in the TRIM9 induced bladder cancer progression." (PMID 37249822, 2023). "Together, our experiments provided evidence that TRIM9 plays an essential role in promoting tumor progression, and described innovative target for bladder cancer therapy." (PMID 37249822, 2023). "Secondly, our exploration about effects of TRIM9 on cell biological processes showed that TRIM9 promoted bladder cancer proliferation, migration and chemoresistance via CEACAM6/Smad2/3 signaling." (PMID 37249822, 2023). "And TRIM9 overexpressed T24-bearing mice exhibited a shorter survival time compared to vector group, indicating that TRIM9 promoted bladder cancer development and resulted in poor prognosis in vivo." (PMID 37249822, 2023). "Motivated by our previous evidence that TRIM9 promoted CEACAM6-Smad2/3 signaling to facilitate bladder cancer cell proliferation/migration, we next sought to evaluated the influence of TRIM9 on tumor growth in vivo." (PMID 37249822, 2023). "Together, those data indicated that TRIM9/CEACAM6 mediated Smad2/3 signaling activation to modulate bladder cancer progression." (PMID 37249822, 2023). "Our evidences highlighted the critical role of TRIM9 in bladder cancer progression and provided promising therapeutic targets for clinical treatment." (PMID 37249822, 2023). "Consistent with prior evidences, the present study initially clarified a pro-tumor function of TRIM9 in bladder cancer development." (PMID 37249822, 2023). "Collectively, those results suggested that TRIM9 mediated bladder cancer progression through CEACAM6." (PMID 37249822, 2023).
bladder cancer (continued). "In attempt to explore the molecular mechanism driven by TRIM9 for promoting bladder cancer development, we further evaluated the transcriptome expression of TRIM9-high patients (n = 148) compared to TRIM-low group (n = 148)." (PMID 37249822, 2023). "In summary, our experiments suggest that TRIM9 plays an oncogenic role in bladder cancer progression by increasing cell proliferation, migration, and inducing chemoresistance via CEACAM6/Smad2/3 signaling pathway." (PMID 37249822, 2023). "Together, those results indicated that TRIM9 played an oncogenic role in promoting bladder cancer development." (PMID 37249822, 2023). "Moreover, blockade of Smad2/3 signaling increased chemo-sensitivity to MMC and GEM in TRIM9 overexpressed cells, indicating that TRIM9 upregulated Smad2/3 to facilitate bladder cancer development and chemoresistance." (PMID 37249822, 2023). "Furthermore, we demonstrated that TRIM9 promoted bladder cancer progression and chemoresistance through the regulation of cell proliferation, apoptosis, migration via CEACAM6-Smad2/3 signaling." (PMID 37249822, 2023). "In the present study, we validated a contribution of TRIM9 to bladder cancer progression." (PMID 37249822, 2023). "In vitro, TRIM9 promoted bladder cancer cells Biu-87 and T24 cell proliferation and migration." (PMID 37249822, 2023). "However, little is known about the expression profile of TRIM9 in bladder cancers, and its biological role in this disease remains unclear." (PMID 37249822, 2023). "We wondered whether elevated TRIM9 influenced overall survival of bladder cancer patients." (PMID 37249822, 2023). "Thus, the TRIM9/Smad2/3 signaling might represent promising prognostic markers and therapeutic targets for bladder cancer." (PMID 37249822, 2023). "Other TRIM proteins (TRIM9, TRIM38, TRIM65, and TRIM66) promoted progression of bladder cancer by targeting GLUT1, ANXA2, and MMP11." (PMID 40723250, 2025). "Mechanically, we further demonstrated that the overexpressed TRIM9 increased tumor cells proliferation, migration and drug resistance via CEACAM6-Smad2/3 signaling activation in bladder cancer." (PMID 37249822, 2023). "Immunostaining indicated that recurrent bladder cancer patients displayed a prominent increase in TRIM9 expression in comparison with non-recurrent group." (PMID 37249822, 2023). "We found that the protein level of MMP9 was unchanged, while TRIM9 overexpression facilitated MMP2 production in Biu-87/T24 cells, and blockade of Smad2/3 signaling suppressed MMP2 expression, indicating that Smad2/3 mediated downstream MMP2 production in bladder cancer cells." (PMID 37249822, 2023).
breast tumor (2 papers, 2015 to 2023). "Although these findings suggest that TRIM9 expression is epigenetically regulated by promoter methylation in BCCs, we could not confirm the occurrence of such an epigenetic regulation in breast tumor tissues." (PMID 26543769, 2015). "We found that TRIM9 promoter hypermethylation occurred in 68 % of breast tumors but not in normal breast tissues." (PMID 26543769, 2015).
esophageal cancer (2 papers, 2023 to 2025). A primary or metastatic malignant neoplasm involving the esophagus. "Next, in order to unveil the underlying molecular mechanism of TRIM9's impact on esophageal cancer, we further explore the expression level association between ZEB1 and TRIM9." (PMID 37124931, 2023). "Results from the TRIM9 mRNA and protein quantification study of esophageal cancer samples suggested that ZEB1 protein levels were significantly correlated with TRIM9 (p < 0.001), but for their mRNA expression levels, no notable correlation was detected." (PMID 37124931, 2023). "In order to investigate the protein expression of TRIM9 in esophageal cancer cells, IHC slides of esophageal cancer samples and corresponding adjacent normal samples were utilized." (PMID 37124931, 2023). "In this study, we demonstrated that a TRIM9 expression decrease was characteristic of esophageal cancer cells." (PMID 37124931, 2023). "In this study, we reported for the first time that TRIM9 was suppressed in esophageal cancer patients." (PMID 37124931, 2023). "Both esophageal cancer samples and cell line models showed significantly suppressed levels of TRIM9." (PMID 37124931, 2023). "Consistent with our findings, TRIM9 mRNA as well as the protein expression pattern was further validated in esophageal cancer cell lines/normal human epithelial cell lines." (PMID 37124931, 2023). "It is worth mentioning that future consolidation studies are still required to consolidate the role of TRIM9 in esophageal cancer patients." (PMID 37124931, 2023). "And TRIM9 inhibited esophageal cancer tumor expansion, invasion, and metastasis through interaction with ZEB1, which accelerated its protein degradation through the UPP pathway." (PMID 37124931, 2023). "We aimed to elucidate the regulatory role of TRIM9 in esophageal cancer." (PMID 37124931, 2023). "Therefore, we aimed to investigate the significance of TRIM9 and its related molecular regulatory network in esophageal cancer." (PMID 37124931, 2023). "Therefore, in the current research, we intended to clarify the regulatory network of TRIM9 and its relative role in esophageal cancer patients." (PMID 37124931, 2023). "The conclusion of this research suggested that aberrant methylation of TRIM9 might also account for the TRIM9 expression suppression in esophageal cancer, which deserved further investigation." (PMID 37124931, 2023). "However, whether TRIM9 could regulate esophageal cancer by affecting ZEB1 remains unclear." (PMID 37124931, 2023). "Functional experiments including transwell assay, cell viability assay, and ubiquitination blocking experiments were performed to evaluate the role of the TRIM9/ZEB1 (zinc finger E-box binding homeobox 1) axis and UPP pathway in esophageal cancer progression and exacerbation." (PMID 37124931, 2023). "However, the exact role of TRIM9 in esophageal cancer exacerbation and metastasis is not clarified." (PMID 37124931, 2023).
glioblastoma (2 papers, 2023 to 2024). The most malignant astrocytic tumor (WHO grade IV). "The functional difference between Trim9-L/TRIM9-L and Trim9-L/TRIM9-S was reported in several biological contexts including neuron morphogenesis and glioblastoma progression, but how the two Trim9/TRIM9 isoforms are regulated remains unclear." (PMID 37665675, 2023).
non-small cell lung carcinoma (2 papers, 2015 to 2019). A group of at least three distinct histological types of lung cancer, including non-small cell squamous cell carcinoma, adenocarcinoma, and large cell carcinoma. "For example, the expression of TRIM9 in non-small cell lung cancer cell lines was significantly lower in HBE cells." (PMID 31028132, 2019).
bladder tumor (1 paper, 2023). "Subsequently, to further validate the role of TRIM9 in tumor recurrence, we obtained 22 clinical bladder tumor tissues, in which patients were divided into recurrent and non-recurrent groups according to 5-years follow-up visit." (PMID 37249822, 2023).
cerebellar ataxia (1 paper, 2024). A neurological syndrome characterized by clumsy and uncoordinated movement of the limbs, trunk, and cranial muscles. "In the cerebellar irAE cohort, patients demonstrated Ab positivity to uncharacterized antigens, high risk Abs, and Abs which have shown association to cerebellar ataxia, though remaining less characterized (anti-TRIM9, neurofilament-light chain, and anti-Zic4)." (PMID 39153058, 2024).
colon cancer (1 paper, 2024). "Five TRIM expression was significantly upregulated (TRIM14, TRIM15, TRIM24, TRIM29, and TRIM31), and the other five TRIM genes showed decreased expression (TRIM1, TRIM3, TRIM9, TRIM22, and TRIM73) in both colon cancer (COAD) and rectal cancer (READ)." (PMID 38769340, 2024).